INS (insulin)
Diseases named in the same sentence as INS in open-access papers (continued):
Sharing a sentence is not in itself a finding about the gene and the disease.
lung carcinoma (continued). "For non-insulin anti-diabetics, the proportion of adherent survivors decreased by 4 to 7 percentage points among those diagnosed with colorectal and lung cancer." (PMID 34843550, 2021). "On the other hand, insulin is one of the main stimuli of the Ras signaling pathway which plays a key role in the onset of lung cancer." (PMID 33777737, 2021). "Data regarding the effects of antihyperglycemic therapy, especially treatment with insulin, on lung cancer outcomes are sparse and conflicting." (PMID 32156062, 2020). "Though insulin treatment also showed a survival advantage, there is still little published data on the insulin effect on the survival of patients with lung cancer." (PMID 32156062, 2020). "The main objective of our study was to evaluate the effect of metformin-based therapy and insulin-based therapy on the survival of patients with lung cancer." (PMID 32156062, 2020). "Compared to the referent subgroup of insulin (–)/COPD (–), all the other three subgroups showed a significantly higher risk of lung cancer." (PMID 31354621, 2019). "Exposure to human insulin and incidences of lung cancer and hazard ratios comparing exposed to unexposed." (PMID 31354621, 2019). "Lung cancer patients with GLC > 99 mg/dL had significantly higher serum INS, C-PEP and HOMA-IR levels compared to patients with GLC ≤ 99 mg/dL, or with control subjects." (PMID 30235348, 2018). "Metformin has been found to be more effective in inhibiting tumor growth in obese and insulin-resistant animals than in their lean counterparts in breast and lung cancer models." (PMID 29444159, 2018). "Using MR-Base, we also evaluated the association between cigarette smoking for each genetic instrument associated with lung cancer risk, including BMI, LDL, and fasting insulin." (PMID 28594918, 2017). "Metformin has been found to be more effective in inhibiting tumor growth in obese and insulin resistant animals versus their lean counterparts in breast and lung cancer models 38,39." (PMID 25417601, 2015). "In lung cancer, miR-486 regulates the insulin growth factor signaling pathway by targeting insulin-like growth factor 1 (IGF1), IGF1 receptor (IGF1R), and phosphoinositide-3-kinase, regulatory subunit 1 (alpha) (PIK3R1)." (PMID 26966540, 2015). "In agreement with the effects of CCC in the 3T3-L1 adipocytes, CCC attenuated insulin-induced Akt phosphorylation in A549 lung cancer cells." (PMID 25181477, 2014). "Based on our previous experiments on lung cancer cell lines and other studies, we anticipated that insulin therapy would regulate the expression of pulmonary surfactant-associated genes." (PMID 25278226, 2014). "A potential link between the insulin signaling pathway and lung cancer came from a study showing that overexpression of the insulin receptor in lung cancer is associated with increased risk of metastasis and decreased survival." (PMID 24212773, 2011). "Ample clinical and laboratory data indicate a critical role for insulin/IGF-1 signaling in lung cancer." (PMID 20642846, 2010). "Verteporfin has been demonstrated to effectively restrain the proliferation and migration of lung cancer cells through the modulation of the Hippo signaling pathway and insulin secretion with the experimental evidence of in vitro cytotoxicity and apoptosis assays and in vivo xenograft models." (PMID 38994794, 2024). "The mechanisms by which lung cancer contributes to elevated blood glucose include: 1) Chemotherapy-Induced Pancreatic Damage: Certain chemotherapy agents can harm pancreatic islet cells, impairing insulin synthesis and secretion." (PMID 39687887, 2024). "Subpathway analysis indicates that verteporfin may influence lung cancer by modulating the Hippo signaling pathway and insulin secretion, consistent with literature findings." (PMID 38994794, 2024). "For this experiment, we used A549 lung cancer cell line, which is highly responsive to insulin." (PMID 38065968, 2023).
lung carcinoma (continued). "Our study showed that insulin was associated with a non-significantly increased risk of lung cancer (aHR 2.11, 95%CI 0.99–4.49) in people with T2D and COPD." (PMID 37242426, 2023). "Prior studies have elucidated that IGF-1 is elevated in patients with lung cancer, suggesting that elevated circulating insulin may play a role in lung cancer." (PMID 36048786, 2022). "We examined if insulin regulated BMPR2 in lung cancer cells." (PMID 35641992, 2022). "We performed a two-sample Mendelian randomization (MR) study to investigate the causal relationship between potentially modifiable risk factors (namely smoking behavior, alcohol intake, anthropometric traits, blood pressure, lipidemic traits, glycemic traits, and fasting insulin) and lung cancer." (PMID 34662362, 2021). "For example, elevated insulin levels may potentiate the activity of insulin-like growth factor-I, which represents a potent growth-promoting factor for lung cancer, and insulin may stimulate the Ras signaling pathway to promote lung carcinogenesis." (PMID 34869022, 2021). "Twelve outcomes including four insulin-related and two lung cancer outcomes demonstrated nominal significance using the inverse variance–weighted (IVW) method, although only evidence of a protective effect for ischemic stroke survived multiple testing correction." (PMID 31998841, 2020). "Our results show that exposure to insulin was associated with a lower risk of lung cancer-specific mortality, but not with deaths from all causes." (PMID 32156062, 2020). "An in vitro study using non-small-cell lung cancer cells suggested that insulin promotes the proliferation, migration, and invasion of lung cancer by increasing the phosphorylation of IR substrate 1 and activating the phosphoinositide 3-kinase/protein kinase B pathway." (PMID 31354621, 2019). "This may be particularly so if the data were not missing at random (i.e., if missing data were related to the exposure of insulin use or the outcome of lung cancer)." (PMID 31354621, 2019). "The expression of SLC2A5 is reported to be regulated by many factors such as substrate level, tumor hypoxia, oncogene, inflammatory factor TNF-α, and hormone levels (insulin, thyroxine, etc.)in other tumors, but its modulation in lung cancer remain unknown." (PMID 29531835, 2018). "Previous studies have shown that GnRH and insulin have a correlation with lung cancer." (PMID 30400814, 2018). "Insulin use increased lung cancer risk, while sulfonylureas and TZDs did not significantly have an association with lung cancer risk." (PMID 24924771, 2014). "Likewise, insulin and insulin secretagogues have been shown to be related to higher lung cancer incidence and cancer-related mortality." (PMID 24924771, 2014). "As for site-specific cancers, liver cancer (11.9 per 10,000 patients per year) showed the highest incidence rate in the insulin use cohort, while lung cancer (12.0 per 10,000 patients per year) exhibited the highest incidence rate in the non-insulin use cohort." (PMID 23308218, 2013). "This has led to the hypothesis that inhaled insulin may have potential for use in the early detection of lung cancer." (PMID 24212773, 2011). "Insulin also stimulates the Ras signaling pathway, which is important in lung carcinogenesis and may also stimulate local angiogenesis or promote tumor cell growth through insulin receptors on lung cancer cells." (PMID 38902745, 2024). "Similarly, A549 was the only lung cancer cell line that recovered following ARG/insulin treatment." (PMID 38374190, 2024). "Insulin therapy in patients with COPD may need close monitoring for the occurrence of lung cancers." (PMID 37242426, 2023).
lung carcinoma (continued). "Meanwhile, elevated insulin may increase the risk of lung cancer, but no other study has explored the impact of other glycemic traits on lung cancer." (PMID 34662362, 2021). "Additionally, multiple studies have reported that use of insulin sensitizers, such as metformin and TZD in COPD may improve lung functions and reduce risks of all-cause mortality and lung cancer." (PMID 33267895, 2020). "Whether insulin glargine or other insulin analogs may also increase the risk of lung cancer was not addressed here and is an issue awaiting urgent investigation." (PMID 31354621, 2019). "Additionally, metformin was found to possibly underlie its ability to prevent the development of lung cancer by reducing circulating levels of IGF-I and insulin and mediate its effects through inhibition of the IGF-I/insulin receptor signaling and receptor tyrosine kinases (RTK) signal pathways." (PMID 27105507, 2016). "None of the medications including insulin would affect the risk of lung cancer." (PMID 24991802, 2014). "Furthermore, the ability to upregulate the insulin dependent glucose transporter Glut-4 may be of clinical benefit in the early detection of lung cancer as a combination of HDACi and inhaled insulin may enhance FDG-PET imaging." (PMID 24212773, 2011). "Previous studies have reported that neutrophil infiltration in the liver of obese mice impairs insulin signaling through elastase-mediated degradation of IRS1, a phenomenon also observed in lung cancer research." (PMID 40305335, 2025). "We reveal that activated Rab37 promotes the secretion of insulin in mouse β cells (Min‐6) and TIMP1 in human lung cancer cells (CL1‐5‐Q89L, harboring active Rab37), respectively." (PMID 38804615, 2024). "However, the direction of OR suggested high fasting insulin level could increase the risk of lung cancer, though not significant, suggesting a lack of statistical power of IVs for fasting insulin in our study." (PMID 34662362, 2021). "On the one hand, insulin can promote the activity of insulin-like growth factor (IGF-I), which is an effective growth factor in promoting lung cancer growth." (PMID 33777737, 2021). "GLUT4 can be expressed in insulin-sensitive tissues, fat and muscle, GLUT4 can also be found in 6.6% of lung carcinomas, whereas GLUT1 is expressed in 74% of lung-carcinomas samples." (PMID 32596143, 2020). "In this study increased serum insulin, C-peptide concentrations and HOMA-IR value observed in lung cancer patients were evidently direct consequences of elevated circulating glucose concentration." (PMID 30235348, 2018). "Insulin is known to stimulate the proliferation of tumor cells both directly and indirectly by acting upon IGF-1 receptors expressed on lung cancer." (PMID 24924771, 2014). "However, whether insulin use would increase the risk of lung cancer is an issue that has not been extensively investigated." (PMID 24991802, 2014). "Therefore, the use of exogenous insulin may further contribute to neoplastic growth of lung cancer." (PMID 24924771, 2014). "Our data are strongly in agreement with previous indication that GAPDH is regulated in response to various stimuli (i.e hypoxia, insulin, mitogen, EGF) and that its transcript is elevated in various cancer tissues, including lung cancer." (PMID 16872493, 2006). "We already confirmed that either high glucose or serum starvation could activate Rab37 and induce secretory autophagy to promote exocytosis of insulin from β‐cell and TIMP1 from lung cancer cells." (PMID 38804615, 2024). "Interestingly, the IGF axis is a complex molecular network (including peptide‐ligands IGF1, IGF2, and insulin, and the receptors IGF1R, IGF2R, and INSR) that is involved in a wide variety of neoplasms such as prostate, breast, colorectal, and lung cancers." (PMID 34668636, 2022).
lung carcinoma (continued). "It is important to note, however, that stimulation of human A549 lung cancer cells and primary mouse lung cancer cells with several different growth factors (e.g., EGF; FBS; insulin) increased TBK1 S172 phosphorylation, which required TBKBP1 (TBK1 binding protein 1), a TBK1 adaptor protein." (PMID 34245780, 2021). "The Kaplan-Meier survival analysis showed differences for lung cancer-specific survival between non-diabetic and diabetic patients by antihyperglycemic medication user groups, with better survival in the groups of insulin and metformin users." (PMID 32156062, 2020). "Because lung cancer cells may overexpress IR-A and IGF-1R, the binding of insulin to these receptors triggers the mitogenic pathways." (PMID 31354621, 2019). "Incidence rates of lung cancer for never-users, ever-users, and tertiles of three dose-response exposure parameters (i.e., time since starting insulin, cumulative dose, and cumulative duration) were calculated." (PMID 31354621, 2019). "In addition, metformin, which is an oral antidiabetic drug administered to improve insulin sensitivity, reduced miR-222 expression in cancer cell lines such as A549 and NCI-H358 human lung cancer cell lines." (PMID 29364977, 2018). "Lung cancer tumorspheres are typically isolated in serum-free media supplemented with external mitogens such as epidermal growth factor (EGF), basic fibroblast growth factor (bFGF), and insulin." (PMID 26880969, 2016). "Insulin or other medications are not, but COPD and lower socioeconomic status are significantly associated with lung cancer." (PMID 24991802, 2014). "For example, lung (location of lung cancer) and pancreas (location of insulin), were not indexed as major topics." (PMID 23742159, 2013). "Klotho could also inhibit proliferation and increase apoptosis of human lung cancer A549 cells, which may be partly due to the inhibition of IGF-1/insulin pathways and involving regulating the expression of the apoptosis-related genes bax/bcl-2." (PMID 23516476, 2013). "Since secreted klotho protein can inhibit the activation of insulin/IGF-1 receptors, we presumed that klotho may also function as a suppressor of lung cancer." (PMID 20642846, 2010). "Multiple lines of evidence suggest the involvement of the IGF-1/insulin pathways across a range of malignancies, including both NSCLC and small cell lung cancer (SCLC), and inhibition of IGF-1 signaling pathway is a potential therapy for human lung cancer." (PMID 20642846, 2010). "Unlike BMP2, insulin activated Akt in lung cancer cells during starvation." (PMID 35641992, 2022). "However, since insulin measurement is not a routine examination for lung cancer patients, its clinical application is limited." (PMID 33777737, 2021). "In the analysis stratified by control group drugs, a no-drug or insulin study had a null relationship between the incidence of lung cancer and metformin in diabetic patients (RR = 0.89; 95% CI, 0.77-1.03; P = 0.13 and RR = 0.97; 95% CI, 0.75-1.26; P = 0.84, respectively)." (PMID 30881522, 2019). "Moreover, IGF signaling has been previously involved in keeping human lung cancer cell stemness while IGF1R downregulation, in conjunction with INSR inhibition, was more effective in blocking IGF- and insulin-mediated signaling and growth in cancer cells compared to single-receptor targeting alone." (PMID 27861515, 2016). "Indeed, insulin and IGF-1 not only stimulated TRB3 expression in human HepG2 cells in time-dependent and concentration-dependent manners by activating TRB3 transcription 17, but also enhanced TRB3 expression in human colon and lung cancer cells." (PMID 26268733, 2015).
lung carcinoma (continued). "In summary, klotho, a potential tumor suppressor, can inhibit the growth of lung cancer cells A549 and promote their apoptosis, this may be partly due to the inhibition of IGF-1/insulin pathways and involving regulating the expression of the apoptosis-related genes bax/bcl-2." (PMID 20642846, 2010). "Furthermore, a higher fasting insulin level could not lead to lung cancer (OR = 1.42 [0.50, 4.03], p-value = 0.514)." (PMID 34662362, 2021). "Furthermore, insulin and COPD might jointly enhance the development of lung cancer." (PMID 31354621, 2019). "Similarly, insulin and IGF-1, no matter they activate or not the autophagic signals, induced a significant accumulation of insoluble p62 in human liver, colon and lung cancer cells." (PMID 26268733, 2015).